BDNF (brain derived neurotrophic factor)
Diseases named in the same sentence as BDNF in open-access papers (continued):
Sharing a sentence is not in itself a finding about the gene and the disease.
schizophrenia (continued). "Future studies should look into the novel potential roles of BDNF in schizophrenia including regulation of inflammation, modulation of mitochondria function, epigenetic regulation, and regulation of neural oscillations." (PMID 37077958, 2023). "The main themes and strong research areas of BDNF in schizophrenia include its role as a neurobiological marker (pathogenesis, treatment monitoring, and risk factors), and cognition in schizophrenia." (PMID 37077958, 2023). "We researched the month of walking alone (MWA) and BDNF level between drug-naive first-episode schizophrenia patients (FEP) and healthy control (HC), as well as how they behave in neurocognitive function and severity of symptoms." (PMID 37234686, 2023). "Correlation between positive and negative symptoms scale (PANSS) total score and serum Brain derived neurotrophic factor (BDNF) in schizophrenia patients." (PMID 37485797, 2023). "In our study, we observed a significant decrease in brain-derived Neurotrophic factor (BDNF) levels in the schizophrenia group, while the methamphetamine addiction group showed higher BDNF levels compared to the healthy control group." (PMID 37520481, 2023). "In contrast, schizophrenia patients exhibited a correlation between a greater decrease in BDNF blood levels and disease duration, whereas plasma BDNF, but not serum, levels were increased after antipsychotic treatment in schizophrenia patients." (PMID 37763162, 2023). "With regard to the mechanism of action, ECT induces an increase in serum BDNF levels in schizophrenia." (PMID 37685795, 2023). "This study aimed to determine the role of serum BDNF levels in schizophrenia and methamphetamine addiction." (PMID 37520481, 2023). "Reduced levels of BDNF have been observed in the brain of people with schizophrenia, particularly in regions involved in cognitive processes, such as the prefrontal cortex and hippocampus." (PMID 37109038, 2023). "In the analysis performed, the majority of studies confirmed reduced peripheral BDNF levels in schizophrenia, whereas two studies reported higher serum BDNF concentrations or serum protein in schizophrenia compared with healthy controls." (PMID 36831706, 2023). "Participants with schizophrenia had a significantly lower median level of BDNF (0.36 pg/ml) compared to the control group (0.51 pg/ml) and the methamphetamine group (0.72 pg/ml)." (PMID 37520481, 2023). "What are the research trends and changes in the authors' knowledge network related to recent literature on schizophrenia and BDNF?" (PMID 37077958, 2023). "Brain derived neurotrophic factor (BDNF) is thought to be involved in the pathogenesis of schizophrenia." (PMID 37485797, 2023). "Another biomarker studied in patients with schizophrenia is brain-derived neurotrophic factor (BDNF)." (PMID 36979300, 2023). "We did not come across any comparative analyses in the literature that specifically investigated the genetic BDNF variants in relation to selected mental disorders in our study, namely MDD or schizophrenia." (PMID 37626739, 2023). "Future research is anticipated to concentrate on relevant subjects, such as factors that affect BDNF levels or are connected to BDNF dysfunction in schizophrenia, as well as animal models of schizophrenia, in addition to cognition in schizophrenia." (PMID 37077958, 2023). "Recent clinical studies analyzed the effects of curcumin on BDNF levels in schizophrenia or the beneficial effects of add-on therapy combined with antipsychotic treatment in patients with chronic schizophrenia." (PMID 36946488, 2023). "Neurodevelopmental model of schizophrenia suggest that reduced levels of BDNF alter neurotransmission through decreased synaptic connectivity resulting in the appearance of symptoms." (PMID 36767478, 2023).
schizophrenia (continued). "There was not a significant effect of exercise on the psychological biomarkers (e.g., cortisol, dehydroepiandrosterone, or brain-derived neurotrophic factor) of patients with schizophrenia (k = 3; N = 4; g = −0.12, [95% CI –0.40, 0.17])." (PMID 37096668, 2023). "The first article on the topic of BDNF in schizophrenia was published in the American Journal of Medical Genetics in 1997." (PMID 37077958, 2023). "In the present study, the serum BDNF expression level was lower in drug-naïve patients with first-episode schizophrenia than in the healthy control group, and it was smaller in the depressive patient subgroup than in the non-depressive patient subgroup." (PMID 37013544, 2023). "Reductions in distinct BDNF transcripts in the DLPFC (BDNF II), parietal cortex (BDNF II and IV) and hippocampus (BDNF VI) occur in schizophrenia." (PMID 35628144, 2022). "Although BDNF is likely the best-studied neurotrophin both in basic research and in relation to various clinical syndromes, studies on the concentrations of BDNF serum levels in patients with schizophrenia have had contradictory results." (PMID 35873262, 2022). "PPI behavioral deficits that were reversed by local infusion of BDNF in Dtnbp1 knockout mice with schizophrenia-like behavior underscores the importance of DTNBP1 in regulating BDNF secretion and its role in the development and treatment of schizophrenia." (PMID 35815020, 2022). "Since its publication, there has been additional studies reporting data on BDNF levels in schizophrenia." (PMID 35447946, 2022). "Some animal models of schizophrenia confirm the down-regulation of BDNF levels observed in the post-mortem studies of brains of schizophrenic patients." (PMID 35216241, 2022). "It has been reported that patients who have schizophrenia had serum levels of BDNF significantly lower than controls." (PMID 35628626, 2022). "For example, a meta-analytic study published in 2015 showed a decrease of both drug naive and medicated schizophrenia patients peripheral BDNF levels when compared to healthy controls." (PMID 35447946, 2022). "There was a significant difference in the BDNF gene rs11030101/rs2030324/rs6265 AAC haplotype frequency between the schizophrenia and control groups (p < 0.05)." (PMID 35368680, 2022). "Patients with depressive symptoms in the early stages of schizophrenia were shown to have higher levels of BDNF in their serum." (PMID 35757201, 2022). "Meta-analysis showed a correlation between a decrease in BDNF and cognitive functioning in schizophrenia." (PMID 35163141, 2022). "S100 protein, nerve growth factor, and brain-derived nerve factor (BDNF) are also potentially important biomarkers of schizophrenia." (PMID 36387009, 2022). "A number of studies have shown that the serum BDNF levels of patients with schizophrenia were lower than those of healthy controls." (PMID 35757201, 2022). "Accordingly, to determine how serum BDNF levels influence depressive symptoms in patients with FEDN schizophrenia, more research needs to be done." (PMID 35757201, 2022). "In this study, we examine the expression of two influential factors, TTP and miR-16, in patients with schizophrenia that can disrupt the regulated expression level of BDNF in a case-control study." (PMID 36476595, 2022). "The aim of the study was to search for associations between BDNF, CRP, IL-6 and clinical symptoms, cognitive and personal performance in patients with paranoid schizophrenia." (PMID 35873262, 2022). "Studies have shown that BDNF levels are decreased in the prefrontal cortex and hippocampus in patients with schizophrenia." (PMID 35447946, 2022). "Results concerning brain-derived neurotrophic factor (BDNF) levels and their factors (such as substance use) in schizophrenia have been partly contradictory." (PMID 35873262, 2022).
schizophrenia (continued). "In most studies involving MDD, serum BDNF levels correlated negatively with disease severity, and antidepressant treatment increased serum levels of BDNF, as do antipsychotics in schizophrenia." (PMID 35114967, 2022). "The DNA methylation status of the BDNF gene was reportedly altered in a prenatal stress mouse model of schizophrenia with a consequent decrease in BDNF mRNA and enrichment of 5-methylcytosine and 5-hydroxymethylcytosine at BDNF gene regulatory regions." (PMID 35887357, 2022). "Comparatively, in individuals with schizophrenia, the ratio of BDNF pro-peptide to total protein level in CSF was also markedly lower in male patients compared to female patients." (PMID 35887357, 2022). "In the brain of schizophrenia individuals, the dorsolateral prefrontal cortex was shown to contain significantly lower BDNF protein and mRNA, along with decreased TrkB expression, compared to healthy controls." (PMID 35887357, 2022). "Levels of BDNF in the hippocampus and prefrontal cortex have been demonstrated to be lower in patients with schizophrenia." (PMID 35757201, 2022). "Studies have found that serum BDNF levels in adult schizophrenia patients are usually lower than in normal controls." (PMID 36261468, 2022). "Epigenetic modification of BDNF was found in postmortem brains of schizophrenic individuals and in brains of mice with schizophrenia-like behavioral abnormalities born from prenatal stress mice." (PMID 35853898, 2022). "There is also a contradictory evidence for both the elevation and reduction of BDNF levels in the frontal cortex and in the Hip in the course of schizophrenia." (PMID 35269761, 2022). "Genotype data for the rs11030101, rs2030324, and rs6265 polymorphisms in the BDNF gene and the rs6740584 and rs2551640 polymorphisms in the CREB gene for 134 patients with schizophrenia were tested for Hardy–Weinberg equilibrium." (PMID 35368680, 2022). "Serum BDNF levels in patients with FEDN schizophrenia were significantly lower than those in healthy controls (p < 0.001)." (PMID 35757201, 2022). "The levels of BDNF in blood, cerebrospinal fluid, and different brain regions of schizophrenia patients are low." (PMID 36246525, 2022). "The goal of the present study was to assess the plausibility of using peripheral BDNF levels as a marker for diagnosis of schizophrenia and treatment response to antipsychotic drug treatment." (PMID 35447946, 2022). "Although some evidence indicates a decrease in BDNF in serum from patients with schizophrenia, other studies have shown its elevated level." (PMID 35269761, 2022). "The abnormality of BDNF is closely related to schizophrenia and plays a key role in learning and memory." (PMID 36246525, 2022). "Post-mortem studies of schizophrenia patients’ brains revealed alterations in BDNF in certain brain regions." (PMID 35216241, 2022). "miR-137 regulates the expression of schizophrenia-associated genes and contributes to the regulation of neuronal response by targeting the PI3K-Akt-mTOR branch of neuregulin-1/ErbB and BDNF signaling." (PMID 35916975, 2022). "Both BDNF and oxytocin exert an influence on psychiatric disorders, such as social behavior, autism, schizophrenia, and mood and anxiety disorders." (PMID 35721318, 2022). "In this regard, BDNF relationship with cognitive dysfunction in patients with different stages of psychosis, including but not limited to chronic schizophrenia, accumulates growing evidence." (PMID 35873262, 2022). "The rs11030101, rs2030324, and rs6265 loci in BDNF play an important role in the occurrence and development of schizophrenia." (PMID 35368680, 2022). "In this study, serum BDNF levels were lower in patients with FEDN schizophrenia than in healthy controls, confirming our prior studies and consistent with other studies in patients with first-episode schizophrenia, and chronic schizophrenia, albeit not all." (PMID 35757201, 2022).
schizophrenia (continued). "Although the relationship between BDNF and schizophrenia is complex, these findings suggest that the degree of BDNF transmission can be targeted to alter, and potentially restore, the balance of dopaminergic transmission in schizophrenia." (PMID 35955546, 2022). "Most meta-analyses concur that serum levels of BDNF in unmedicated and medicated individuals with schizophrenia are reduced and that BDNF levels decrease further with age." (PMID 35887357, 2022). "Due to the lack of strong evidence and small sample size, studies describing the correlation between BDNF rs6265 and schizophrenia are still contradictory." (PMID 36325525, 2022). "Studies reported an altered BDNF expression in the cortical areas of the brain of schizophrenia patients." (PMID 34831111, 2021). "In the case of schizophrenia, diminished BDNF concentration levels were observed, as well as their normalization after antipsychotic medication." (PMID 34640441, 2021). "We investigated the associations of DRD3 rs6280, HTR1A rs6295, BDNF rs6265, SCL6A4 rs16965628, and 5HT2A rs7322347 with schizophrenia in a case–control study, and associations of these genetic variants with several clinical features." (PMID 34025476, 2021). "Psychopharmacological treatment has modulating effects on BDNF and TNFα in drug-naïve first-episode patients with either schizophrenia or MDD." (PMID 33653423, 2021). "They concluded that parallel changes in BDNF levels in plasma and CSF indicate that plasma BDNF levels reflect the brain changes in BDNF levels in schizophrenia." (PMID 34220575, 2021). "The correlation table showed the relationships between the Kyn pathway metabolites and the cytokines (TNF-α, IL-6), hsCRP, and BDNF in the schizophrenia group and the healthy control group." (PMID 34393855, 2021). "Despite awareness of the need for early interventions, fewer studies on BDNF and cognition are found in patients with a first psychotic episode than in patients with established chronic schizophrenia." (PMID 34220575, 2021). "Brain-derived neurotrophic factor (BDNF), as an important neuroplastic molecule, has been reported to be involved in neurocognitive impairment in schizophrenia." (PMID 34239458, 2021). "The PANSS negative syndrome and PANSS total scores are negatively correlated with the BDNF serum level in patients with schizophrenia." (PMID 34434228, 2021). "According to other studies patients with schizophrenia accompanied by catatonic symptoms are found to have lower serum BDNF levels, which proves the link between BDNF and catatonia symptoms." (PMID 34025476, 2021). "It has previously been demonstrated that patients with schizophrenia have lower serum BDNF, MBP, and GFAP levels, but higher serum IL-6 and S100B." (PMID 34025476, 2021). "In the schizophrenia patients, on the 20th day of treatment, there was a statistically significant increase in BDNF compared to the 1st day of treatment." (PMID 34763683, 2021). "We also evaluated the serum levels of cytokines (TNF-α, IL-6), hsCRP, and BDNF in patients with schizophrenia and healthy controls." (PMID 34393855, 2021). "As studies indicated the potential role of miR-195 in controlling brain BDNF expression, it is possible that via affecting BDNF level also in the peripheral blood, miR-195 is harmful for cognitive functions of schizophrenia patients." (PMID 33558459, 2021). "While most studies on serum BDNF levels in patients with schizophrenia have found low serum BDNF levels, in a few studies, BDNF levels were found to be high." (PMID 34763683, 2021). "In a sensitivity analysis including only high-quality studies, our results of increased BDNF after treatment in schizophrenia remained the same with a similar effect size." (PMID 33653423, 2021). "Cognitive impairments in schizophrenia are associated with neuroinflammatory markers such as CRP, S100B and neuron-specific enolase, and with lower concentrations of BDNF." (PMID 34025476, 2021).
schizophrenia (continued). "In one meta-analysis, serum BDNF levels of patients with schizophrenia were found to be lower than those of healthy controls, regardless of drug use." (PMID 34763683, 2021). "Our results indicate some evidence for a potential causal role of a number of immunological proteins/traits in schizophrenia including IL-6, sIL-2Rα, IL-9, MCP-1 and BDNF." (PMID 34280516, 2021). "Despite being beyond the focus of our review, studies in animal models of schizophrenia and pre-clinical studies with post-mortem brain tissue in humans are an active field of BDNF research that can be found in other review articles." (PMID 34220575, 2021). "Alternatively, it is possible that the BDNF gene expression abnormality is the primary deficit, leading to reduced BDNF protein levels in schizophrenia." (PMID 33558459, 2021). "MDD patients also showed increased BDNF following treatment with a similar effect size as compared with schizophrenia (g: 0.51; CI 0.06–0.96; p = 0.027; I2 = 76%)." (PMID 33653423, 2021). "In patients diagnosed with schizophrenia in monotherapy with an atypical antipsychotic, positive correlations have been observed between BDNF levels in serum and scores for verbal memory, attention, and processing speed." (PMID 34220575, 2021). "The aim of this study was to research the associations between symptomatology and SNP of genes related to the systems of neurotransmission (DRD3 rs6280, HTR1A rs6295, 5HT2A rs7322347) and neurotrophic factor (BDNF rs6265) in schizophrenia patients." (PMID 34025476, 2021). "This study examining the levels of BDNF in the blood in vivo for geriatric patients with schizophrenia indicated a reduction of blood BDNF persists with age and also provided evidence for the association between blood and brain BDNF levels." (PMID 34239458, 2021). "A significant positive correlation was found between the serum level of BDNF and the serum level of 5-HT (r = 0.49, p = 0.0061) and the 5-HT/Trp value (r = 0.55, p = 0.0018) in the schizophrenia group." (PMID 34393855, 2021). "Negative correlations were found between the PANSS-T scores and serum levels of IL-6 and between the PANSS-G scores and serum levels of BDNF in the schizophrenia group." (PMID 34393855, 2021). "The search for molecular biomarkers of cognition has been an important field of research in patients with schizophrenia, in which BDNF has been identified as one of the main ones, along with others such as inflammatory markers." (PMID 34220575, 2021). "Using the Repeatable Battery for the Assessment of Neuropsychological Status (RBANS), the brain-derived neurotrophic factor (BDNF) levels were lower in patients with chronic schizophrenia." (PMID 33882965, 2021). "There was weak evidence that increased levels of BDNF decreased schizophrenia (Wald Ratio OR=0.97; 95% C.I., 0.94-1.00) and bipolar disorder (Wald Ratio OR=0.97; 95% C.I., 0.94-1.00) risk." (PMID 34280516, 2021). "Brain-derived neurotrophic factor (BDNF) is reported to be involved in cognitive decline in patients with schizophrenia (SZ)." (PMID 34625629, 2021). "In fact, HERV-W/MSRV induces activation of the Brain-derived neurotrophic factor (BDNF) and Dopamine receptor D3 (DRD3) genes, both implicated in providing a higher risk for suffering schizophrenia." (PMID 34073730, 2021). "Other determinants, potentially affecting BDNF level in patients with schizophrenia, like age, gender, BMI, smoking, antipsychotic generation (all atypical), and doses, were not different or statistically different between the R and NF groups." (PMID 34434228, 2021). "It was observed that reduced levels of BDNF are related to lower cognitive capacities in patients with schizophrenia." (PMID 34576069, 2021). "We aim to provide an update of BDNF as a biomarker of cognitive function on human subjects with schizophrenia or earlier stages of psychosis, covering new trends, controversies, current research gaps, and suggest potential future developments in the field." (PMID 34220575, 2021).